RBM39 (RNA binding motif protein 39)
Diseases named in the same sentence as RBM39 in open-access papers (continued):
Sharing a sentence is not in itself a finding about the gene and the disease.
colorectal adenocarcinoma (1 paper, 2022). The most common type of colorectal carcinoma. "Previous studies have shown that RBM39 is involved in biological processes in colorectal adenocarcinoma development, such as cell survival and anchoring non‐dependent growth." (PMID 35989423, 2022).
diabetes (1 paper, 2021). "Four genes including GAB2, LMNB2, XAB2 and RBM39 are involved in the regulation of diabetes, fat and insulin signaling, according to text mining." (PMID 34084770, 2021).
endometriosis (1 paper, 2024). The growth of functional endometrial tissue in anatomic sites outside the uterine body. "Moreover, cyto-hub gene analysis revealed that CSNK2A1, CSNK2A2, TOP1, PRKACA, RBM39 (plasma), ALB, ACTB, GAPDH, FN1, APOA1 (serum), S100-A9, CXCL1, IL1RN, CSTA, S100-A8 (menstrual blood) and THBS1, ALB, CD44, ANXA2, and LUM (urine) were the top 5 proteins expressed in women with endometriosis." (PMID 39061077, 2024).
glioma (1 paper, 2025). A benign or malignant brain and spinal cord tumor that arises from glial cells (astrocytes, oligodendrocytes, ependymal cells). "RBM39 depletion has been shown to suppress NF-κB signaling, and inhibition of NF-κB is known to reduce MGMT transcription and sensitize glioma cells to TMZ." (PMID 41300971, 2025).
influenza (1 paper, 2024). An acute viral infection of the respiratory tract, occurring in isolated cases, in epidemics, or in pandemics; it is caused by serologically different strains of viruses (influenzaviruses) designated A, B, and C, has a 3-day incubation period, and usually lasts for 3 to 10 days. "For instance, hsa-miR-6890-5p, CEBPB, Cyclosporine, Influenza, and RBM39 have interactive relationships centered around OAS1." (PMID 38601162, 2024).
leishmaniasis (1 paper, 2022). Infectious disease that is transmitted through the bite of hematophagous female phlebotomine sand flies. "While in LAML, ACC, TGCT and STAD, RBM39 expression negatively regulates anti‐infection responses, including leishmaniasis, common cold and so on." (PMID 35989423, 2022).
meningioma (1 paper, 2026). A generally slow growing tumor attached to the dura mater. "Here we show that sex hormone interaction with PGRMC1, a transmembrane progesterone binding protein, regulates the activity of RNA processing proteins FXR1 and RBM39 to drive meningioma sex differences." (PMID 42282014, 2026).
muscular dystrophy (1 paper, 2022). Muscular dystrophy (MD) refers to a group of more than 30 genetic diseases characterized by progressive weakness and degeneration of the skeletal muscles that control movement. "Three notable exceptions were i) SR-A1 [a.k.a, SCAF1, Serine/Arginine Rich (SR)-related C-terminal domain-associated factor 1] a poorly characterized SR family protein, ii) MBNL1 (Muscleblind-like 1), a RBP known for its role in muscular dystrophy and, (iii) RBM39." (PMID 36477312, 2022).
myeloid malignancies (1 paper, 2023). "In summary, our phase II trial of E7820 in patients with R/R, splicing factor-mutant myeloid malignancies provides proof-of-concept that splicing factor-mutant disease can be targeted in humans via RBM39 degradation." (PMID 37814121, 2023).
osteosarcoma (1 paper, 2016). A usually aggressive malignant bone-forming mesenchymal neoplasm, predominantly affecting adolescents and young adults. "To investigate if RBM39 also negatively regulates BMP4-dependent transcription in human cells, we transfected U2OS osteosarcoma cells with siRNAs to human RBM39 and a BRE-luc reporter." (PMID 27324164, 2016).
ovarian carcinoma (1 paper, 2024). A malignant neoplasm originating from the surface ovarian epithelium. "A recent study demonstrated that the loss of RBM39 induces splicing defects in key DNA damage repair genes, such as ATM and BRCA1, in ovarian cancer, leading to increased sensitivity to cisplatin and various PARPi18." (PMID 38789724, 2024).
prostate carcinoma (1 paper, 2024). A carcinoma that arises from epithelial cells of the prostate gland. "The RNA-Binding Motif Protein 39 (RBM39) splicing factor stimulates the inclusion of a cryptic exon containing a stop signal in the androgen receptor (AR) gene, giving rise to the oncogenic variant AR-V7, the best-characterised AR variant, in prostate cancer." (PMID 38893242, 2024).
retinopathy of prematurity (1 paper, 2021). A bilateral retinopathy characterized by neovascularization, scarring, retinal detachment, and eventually blindness. "RNA binding motif protein 39 (RBM39) were associated with a higher risk of insulin in clinically significant retinopathy of prematurity." (PMID 34084770, 2021).
Wilms’ tumour (1 paper, 2024). "This spliceosomal vulnerability likely extends to other components of the spliceosomal machinery such as HNRNPA1, RBM39 and SNRPD3, as well as other cancers such as Wilms’ tumour, where our transcriptomic analyses revealed MYCN regulation of spliceosome regulators including SNRPD1 and WDR77." (PMID 39313128, 2024).
cancer (62 papers, 2005 to 2026). A tumor composed of atypical neoplastic, often pleomorphic cells that invade other tissues. "We demonstrated that CMTR2-deficient cancer cells exhibit vulnerabilities in the mRNA splicing machinery and are sensitive to RBM39 degraders, such as sulfonamides." (PMID 41198678, 2025). "RBM39 inhibitors induced the intron retention of mRNA of homologous recombination repair (HRR) genes in cancers with homologous recombination deficiency (HRD), causing a synthetic lethality of HRD-positive tumor cells." (PMID 40223119, 2025). "Preclinical studies suggest that aryl sulfonamide-induced RBM39 degradation is a promising cancer therapy, causing widespread splicing errors and strongly inhibiting cancer cell proliferation in vitro and in vivo." (PMID 40465651, 2025). "It has been shown that several types of cancer tissues express high RBM39 mRNA, which is associated with poor patient survival." (PMID 39260689, 2024). "Recently it has been discovered that the RNA-binding motif protein RBM39 is highly expressed in tissues from several cancer patients and its high expression is associated with reduced patient survival." (PMID 39260689, 2024). "Our data bring molecular insights into RBM39-dependent 3′-splice site selection by this cancer-associated splicing factor." (PMID 37666821, 2023). "The anti-cancer sulfonamide E7820 degrades RBM39 and causes global disruption of splicing in preclinical models." (PMID 37814121, 2023). "An increasing amount of evidence reveals that RBM39 is substantially linked to cancer growth in a range of malignancies." (PMID 35989423, 2022). "To assess the link between RBM39 expression levels and prognosis, we ran a survival association study for each cancer, including OS, DSS and PFI." (PMID 35989423, 2022). "RNA-binding protein 39 (RBM39) is associated with pre-mRNA splicing factors; its inactivation by indisulam caused aberrant pre-mRNA splicing in many cancer cell lines." (PMID 30464224, 2019). "In addition, RBM39 expression is associated with the tumour microenvironment and immune cell infiltration in different cancer types." (PMID 35989423, 2022). "We also found that RBM39 expression was associated with age in certain types of cancer." (PMID 35989423, 2022). "An increasing body of data suggests that RBM39 has been closely linked to malignant progression of various cancers, and its expression may be related to RBM39 mutual proteins in specific environments." (PMID 34389703, 2021). "Another aspect of our findings is the recognition that aryl sulfonamides may cause broad metabolic deficiencies and growth inhibition in cancer cells via the mechanism of RBM39 depletion and mis-splicing of specific genes which regulate metabolism and cell cycle." (PMID 35296644, 2022). "RNA-binding motif protein 39 (RBM39) has been reported as a promising therapeutic target for cancer." (PMID 41596295, 2026). "RBM39 is a druggable metabolic sensor that links RNA splicing, transcriptional regulation, and metabolic reprogramming in cancer." (PMID 41596295, 2026). "Increasing evidence supports that splicing homeostasis maintained by RBM39 was essential in tumor progression, which makes RBM39 a promising target of cancer." (PMID 40223119, 2025). "RNA-binding motif protein 39 (RBM39) modulates the alternative splicing of numerous genes involved in cancer occurrence and progression." (PMID 40364450, 2025). "The cancer stem cell enriched KRAS4A isoform was regulated by RBM39, thus providing treatment targeting cancer stem cells." (PMID 40223119, 2025). "Disturbing the splicing of essential oncogenes by targeting RBM39 can be an effective strategy in cancers." (PMID 40223119, 2025). "Pharmacological depletion or siRNA-mediated knockdown of RBM39 led to a marked reduction in MGMT protein levels in MGMT-expressing cancer cells." (PMID 41300971, 2025).
cancer (continued). "Our research also demonstrated that RBM39 degradation was correlated with the inhibition of cancer cell growth, supporting RBM39’s essential role in the growth of cancer cells." (PMID 40227602, 2025). "To date, the arginine binding protein RBM39 and the leucine sensor Sestrin2 have been suggested as targets for indisulam and NV‐5138 for treating cancer and depression, respectively." (PMID 40411419, 2025). "The degradation of RBM39 induced by indisulam treatment leads to aberrant pre-mRNA splicing, which, in turn, induces cell death in cancer cell lines that highly express RBM39." (PMID 40299435, 2025). "As an essential splicing factor, RBM39 regulates ~ 20% of the alternative splicing events in multiple biological processes, including cancers." (PMID 40223119, 2025). "RNA-binding Motif Protein 39 (RBM39), a splicing factor implicated in cancer progression, interacts with transcriptional regulators such as AP-1 and NF-κB, suggesting a potential role in HIV-1 latency." (PMID 41218081, 2025). "The RNA-binding protein RBM39 has been previously shown to be a target of the anti-cancer agent Indisulam." (PMID 40465651, 2025). "RBM39 is overexpressed in many human cancers, including HNSCC, where RBM39 is found to be both highly expressed and negatively correlated with the infiltration of most immune cells." (PMID 40227602, 2025). "Previous studies have also shown that RBM39 is a proto-oncogene that plays an important role in the development of malignant tumors." (PMID 39023715, 2024). "Particularly, JMJD6, which is located on 17q25 and is amplified in a number of cancer types, physically interacts with a subset of splicing factors such as RBM39 and regulates the alternative splicing of metabolic genes." (PMID 38488852, 2024). "Recently it has been demonstrated that RBM39 is a biomarker for different cancers and regulates alternative splicing in cancer cells." (PMID 39260689, 2024). "RBM39 degraders, the anti-cancer sulfonamides indisulam (E7070), E7820, and chloroquinoxaline sulfonamide, selectively degrade RBM39 by promoting interaction of RBM39 and the adapter protein DCAF15 with the CUL4/Db1 E3 ubiquitin ligase." (PMID 39316554, 2024). "Further, we show that JMJD6 is correlated with the anti-cancer activity of indisulam, a ‘molecular glue’ that degrades splicing factor RBM39, which complexes with JMJD6." (PMID 38488852, 2024). "We recently demonstrated that RNA-binding domains of hnRNPU, RBM39 and hnRNPK inhibit the survival of a range of cancer cells." (PMID 38349913, 2024). "Through the two functions, RBM39 participates in cell metabolism, cell cycle, cellular response to hypoxia and angiogenesis, thus plays an important role in cancer cell survival and cancer progression." (PMID 39048555, 2024). "Recent studies have found that RBM39 has been identified as a marker of pan-cancer and is negatively correlated with the infiltration of most immune cells." (PMID 39023715, 2024). "Further, we show that JMJD6 is correlated with the anti-cancer activity of indisulam, a ‘molecular glue’ that degrades the splicing factor RBM39." (PMID 38488852, 2024). "We previously demonstrated that RNA-binding domains of hnRNPK, hnRNPU, and RBM39 act as dominant-negatives and reduce cancer cell growth and viability." (PMID 38349913, 2024). "Strikingly, all three of these pulldowns identified RBM39, an RNA splicing factor known to be upregulated in various cancers but whose particular oncogenic roles remain largely obscure." (PMID 39871876, 2024). "It has been revealed recently that the RNA-binding motif protein RBM39 is highly expressed in several cancers, which results in poor patient survival." (PMID 39260689, 2024). "The small molecule acts as a molecular glue between RBM39 and the DCAF15-CRL4 E3 ubiquitin ligase to induce proteasome-mediated degradation of RBM39 which in turn leads to cancer cell death." (PMID 37666821, 2023).
cancer (continued). "The RNA-binding protein called RNA Binding Motif 39 (RBM39) is overexpressed in several types of cancer and is essential for the survival of many cancer cells including Acute Myeloid Leukaemia (AML) cells." (PMID 37666821, 2023). "The aryl sulfonamide indisulam inhibits the proliferation of several types of cancer cells through its function as a molecular glue to promote the ubiquitination and degradation of RNA-binding motif protein 39 (RBM39)." (PMID 36805336, 2023). "Our work provides molecular insights into RBM39-dependent 3’-splice site selection and constitutes a solid basis to design alternative anti-cancer therapies." (PMID 37666821, 2023). "used a pharmacological compound, indisulam, which enhances the degradation of the RNA-binding motif protein 39 (RBM39), which often is upregulated in cancers." (PMID 37736099, 2023). "In conclusion, our first pan‐cancer RBM39 analysis revealed that it is differentially expressed in tumour and normal tissues and that there is a link between RBM39 expression and clinical prognosis." (PMID 35989423, 2022). "Balmain and colleagues reported that KRAS4A splicing is controlled by the DCAF15/RBM39 pathway, and deletion of KRAS4A or pharmacological inhibition of RBM39 using the splicing inhibitor Indisulam leads to inhibition of cancer stem cells." (PMID 36393833, 2022). "So far, most studies on the role of RBM39 in tumours have been limited to one specific type of cancer." (PMID 35989423, 2022). "Of the 27 tumours we studied in the GTEx and TCGA databases, the RBM39 gene was highly expressed in six cancers and lowly expressed in 19 tumours." (PMID 35989423, 2022). "Then, we used the TCGA database to obtain the differential expression patterns of RBM39 in cancer and paraneoplastic tissue samples." (PMID 35989423, 2022). "As a result, we set out to investigate RBM39’s prognostic significance and putative immunological activities in 33 different cancers." (PMID 35989423, 2022). "Our study showed that RBM39 expression correlated with TMB in 9 cancer types and with MSI in 12 cancer types." (PMID 35989423, 2022). "We investigated the relationship between RBM39 expression and immune‐related genes in 33 malignancies using gene co‐expression analysis." (PMID 35989423, 2022). "Our study also found that the expression of RBM39 in most cancers correlated with tumour stage, and the difference in expression was particularly significant in stage I and II tumours." (PMID 35989423, 2022). "We noticed that RBM39 depletion resulted in missplicing of a number of cancer genes that are involved in cell cycle, apoptosis, signal transduction, DNA repair, metabolism, and epigenetic modifications." (PMID 34788094, 2021). "KRAS4A splicing is controlled by the DCAF15/RBM39 pathway, and deletion of KRAS4A or pharmacological inhibition of RBM39 using Indisulam leads to inhibition of cancer stem cells." (PMID 34257283, 2021). "RBM39 can bind to c-Jun and stimulate its transcriptional activity, promoting its involvement in many aspects of cancer development." (PMID 34804951, 2021). "Taken together, further clinical trials will help determine the use of drugs targeting RBM39 activity in cancer therapy." (PMID 34389703, 2021). "For example, it was found that after indisulam treatment of cultured cancer cells, RBM39 degradation led to altered pre-mRNA splicing, including intron retention and exon skipping, in hundreds of genes." (PMID 33261131, 2020). "RBM39 is involved in RNA splicing activation and transcription in cancer alongside FIR/PUF60." (PMID 41596295, 2026). "In the 3D spheroid cancer models, RBM39 overexpression enhanced holoclone formation." (PMID 40465651, 2025). "RBM39 has been shown to be essential for cancer cell survival both in vitro and in vivo, with the degradation of RBM39 leading to anti-tumoral effects across many cancer cell lines and xenograft models." (PMID 40227602, 2025).